TRAF5 (TNF receptor associated factor 5)
Diseases named in the same sentence as TRAF5 in open-access papers (continued):
Sharing a sentence is not in itself a finding about the gene and the disease.
uveitis (4 papers, 2013 to 2025). An inflammatory process affecting a part of or the entire uvea. "Since the most significant association between TRAF gene polymorphisms and uveitis was found for TRAF5, we studied the effect of the different genotypes on the expression of TRAF5 under normal or inflammatory conditions." (PMID 24416204, 2014). "Highest p values were observed for the association between uveitis and TRAF5, and we therefore focused on this SNP to investigate a possible functional association." (PMID 24416204, 2014). "Two SNPs (rs6540679, rs12569232) of TRAF5 were associated with pediatric uveitis, and rs12569232 also showed a relation with the presence of microvascular leakage." (PMID 24020968, 2013). "The same mutation was also found in pediatric uveitis and significantly in the group showing retinal vascular leakage, which suggests that rs12569232/TRAF5 may play a role in the development of retinal vasculitis." (PMID 24020968, 2013). "Our study investigated the association of TRAF5 with two common forms of uveitis (AAU and pediatric uveitis) and identified rs12569232 polymorphisms were associated with AAU and its subgroups (accompanied by either AS or HLA-B27 positive)." (PMID 24020968, 2013). "Our group is currently studying the role of TRAF5 in other uveitis entities, such as Vogt-Koyanagi-Harada syndrome and Behḉet disease, and data obtained so far confirm the results presented here." (PMID 24020968, 2013). "The current study sought to investigate the potential association of TRAF5 with acute anterior uveitis (AAU) and pediatric uveitis in Han Chinese." (PMID 24020968, 2013). "In view of the findings mentioned earlier, we hypothesized that TRAF5 may also mediate the development of uveitis." (PMID 24020968, 2013). "In total, 458 pediatric uveitis patients were genotyped for three TRAF5 SNPs." (PMID 24020968, 2013). "In the present study, we aimed to determine whether TRAF5 gene polymorphisms were associated with AAU and pediatric uveitis in a Han Chinese population." (PMID 24020968, 2013). "It should also be noted that the GG phenotype of rs12569232 is quite common in China and that TRAF5 is only one gene in a multihit process involving a large number of genes involved in the regulation of an inflammatory immune response, finally leading to the expression of clinical uveitis." (PMID 24020968, 2013). "Uveitis and arthritis have overlapping manifestations, and because the relation between TRAF5 with uveitis has not yet been reported, we decided to investigate the role of TRAF5 polymorphisms in two forms of uveitis, AAU and pediatric uveitis." (PMID 24020968, 2013). "This study revealed that TRAF5 is involved in the development of AAU and pediatric uveitis." (PMID 24020968, 2013). "Whether the same relation exists between the TRAF5 gene and AS patients without uveitis remains to be studied." (PMID 24020968, 2013). "Three TRAF5 SNPs were analyzed in 450 AAU patients with or without ankylosing spondylitis (AS), 458 pediatric uveitis patients, and 1,601 healthy controls by using polymerase chain reaction-restriction fragment length polymorphism (PCR-RFLP) or TaqMan SNP Genotyping Assay." (PMID 24020968, 2013).
coronary heart disease (3 papers, 2016 to 2023). "Additionally, higher systemic levels of TRAF5 are associated with recovery in patients with coronary heart disease." (PMID 37834170, 2023). "An overall anti-atherogenic role of TRAF5 is supported by the fact that TRAF5 mRNA expression is decreased in patients with stable coronary heart disease compared to healthy individuals." (PMID 35252400, 2022). "Therefore, this reflects again that TNF and its co-regulatory genes like TRAF5 might play a crucial role in coronary artery disease." (PMID 27171184, 2016).
hepatocellular carcinoma (3 papers, 2021 to 2025). A malignant tumor that arises from hepatocytes. "Silencing of TRAF5 enhances necroptosis in hepatocellular carcinoma by inhibiting LTBR-mediated NF-κB signaling [Data set]." (PMID 37366426, 2023).
inflammatory bowel disease (3 papers, 2014 to 2020). A spectrum of small and large bowel inflammatory diseases of unknown etiology. "The polymorphisms we used were based on earlier reports showing significant associations with RA, psoriatic arthritis, psoriasis and Inflammatory Bowel Disease and included three SNPs (rs6540679, rs12569232, rs10863888) of TRAF5 and three SNPs (rs13210247, rs33980500, rs13190932) of TRAF3IP2." (PMID 24416204, 2014). "Based on its characteristics of expression, TRAF5 is closely related to many immune-related diseases, such as systemic lupus erythematosus (SLE), inflammatory bowel disease (IBD), and the infection of classical swine fever virus (CSFV)." (PMID 33224951, 2020).
systemic lupus erythematosus (3 papers, 2020 to 2025). An autoimmune multi-organ disease typically associated with vasculopathy and autoantibody production. "A decrease in TRAF5 expression in B cells is linked to the development of autoreactive B cells that are responsible for systemic lupus erythematosus." (PMID 39596396, 2024).
viral infection (3 papers, 2010 to 2025). "To examine whether TRAF5 in fact plays a role in RLR signaling, we tested the effect of the knockdown of TRAF5 expression on signaling activated by transfected poly I:C and viral infection." (PMID 20161788, 2010). "TRAF5 may be a key molecule in the innate response against viral infection." (PMID 20161788, 2010). "The exploration of the TRAF family, particularly TRAF5 and TRAF6, has garnered significant attention within immunological research, especially in the context of viral infections and vaccination responses." (PMID 40136419, 2025). "Together, TRAF5 and TRAF6 serve as critical links between platelet activation and systemic immune dysregulation during viral infections." (PMID 40136419, 2025). "Furthermore, mutations of the binding sites for TRAF2, TRAF5, and TRAF6 on MAVS abolished the ability of MAVS to activate downstream signaling after virus infection, without affecting its ability to form prion-like polymers." (PMID 23951545, 2013).
asthma (2 papers, 2022 to 2024). "The anti-inflammatory and regulatory properties of TRAF5 were further validated in a mouse model of asthma, where TRAF5-deficiency exacerbated lung inflammation by enhanced infiltration of eosinophils and an increased TH2 response." (PMID 35252400, 2022).
Behçet's Disease (2 papers, 2013 to 2014). "Three SNPs (rs6540679, rs12569232, rs10863888) of TRAF5 and rs13210247 of TRAF3IP2 were significantly associated with Behçet's disease and VKH syndrome (corrected P values ranging from 9.45×10−12 to 0.027)." (PMID 24416204, 2014).
diabetic nephropathy (2 papers, 2020 to 2022). "According to several studies, AS-IV protects against diabetic nephropathy by reducing podocyte apoptosis via the lncRNA-TUG1/TRAF5 signaling pathway." (PMID 36675720, 2022). "miR-378 suppresses apoptosis of podocytes through TRAF5 and thereby represses diabetic nephropathy (DN) progression, and it also regulates the protective function of mitogen-activated protein kinase 1 (MAPK1) in the stimulation of kidney cell fibrosis, as well as mesangial hypertrophy." (PMID 33457405, 2020).
glioma (2 papers, 2017 to 2023). A benign or malignant brain and spinal cord tumor that arises from glial cells (astrocytes, oligodendrocytes, ependymal cells). "Another report suggests that NUMBL regulates glioma cells migration and invasion by inhibiting TRAF5-induced NF-κB activation." (PMID 28974699, 2017). "In glioma cells NUMBL has been reported as a suppressor of TRAF5 mediated NF-κB activation." (PMID 28974699, 2017).
Obesity (2 papers, 2020 to 2023). Accumulation of substantial excess body fat. "TRAF5 deficiency also exacerbates diet-induced obesity and metabolic disorders by promoting adipocyte inflammation in mice." (PMID 37330462, 2023).
VKH syndrome (2 papers, 2013 to 2014). "In this study, we show that TRAF5 and TRAF3IP2 gene polymorphisms are associated with VKH syndrome and ocular BD in a Han Chinese population." (PMID 24416204, 2014). "Taken together, our study, for the first time, provides evidence for a role of TRAF5 and TRAF3IP2 polymorphisms in the development of BD and VKH syndrome." (PMID 24416204, 2014). "Although our results suggested that TRAF5 and TRAF3IP2 are associated with the development of BD and VKH syndrome, it is still unknown how these SNPs exert their roles in these two diseases." (PMID 24416204, 2014). "Polymorphisms of the TRAF5 and TRAF3IP2 genes in VKH syndrome." (PMID 24416204, 2014). "This study provides evidence that TRAF5 and TRAF3IP2 genes are involved in the development of BD and VKH syndrome." (PMID 24416204, 2014).
acute lymphoblastic leukemia (1 paper, 2018). Leukemia with an acute onset, characterized by the presence of lymphoblasts in the bone marrow and the peripheral blood. "In addition, apoptosis-resistant B cell-acute lymphoblastic leukemia (B-ALL) cells have aberrantly higher protein level of TRAF5 and TRAF6 in response to irradiation than apoptosis-proficient B-ALL cells." (PMID 30294322, 2018).
Arthritis (1 paper, 2013). Inflammation of a joint. "The reasons for this discrepancy are unclear, but it could point to different roles of TRAF5 in the pathogenesis of arthritis as compared with intraocular inflammation." (PMID 24020968, 2013).
brain cancer (1 paper, 2022). A primary or metastatic malignant neoplasm affecting the brain. "Among them, TRAF5 plays a role in the regulation of the Notch signaling pathway-related NF-κB activation in brain cancer." (PMID 35408801, 2022).
cardiac hypertrophy (1 paper, 2014). "Moreover, deficiency of TRAF5 substantially aggravated cardiac hypertrophy and cardiac dysfunction in response to pressure overload after transverse aortic constriction (TAC)." (PMID 24611063, 2014). "Furthermore, TRAF2 and TRAF5, possible downstream targets of TWEAK/Fn14 signaling, have been implicated in cardiac hypertrophy." (PMID 24611063, 2014).
cardiac ischemia (1 paper, 2023). "Furthermore, rho-miR-125a-5p is related to ischemic stroke and neuronal differentiation, and rho-miR-29b-3p targets genes such as FOXO3a and TRAF5 in a cardiac ischemia-reperfusion model to protect cardiomyocytes from endotoxin-induced apoptosis and inflammation." (PMID 36923213, 2023).
cholangiocarcinoma (1 paper, 2024). A carcinoma that arises from the intrahepatic biliary tree (intrahepatic cholangiocarcinoma) or from the junction, or adjacent to the junction, of the right and left hepatic ducts (hilar cholangiocarcinoma). "Detailed examination indicated that the highest expressions of TRAF1, TRAF2, TRAF3, TRAF5, and TRAF7 were in Cholangiocarcinoma (CHOL), while TRAF4 was most expressed in Uterine Corpus Endometrial Carcinoma (UCEC) and TRAF6 in Glioblastoma multiforme (GBM)." (PMID 38825674, 2024).
chronic renal failure (1 paper, 2020). "Similar protective effects were reported for berberine against chronic renal failure mediated via tumor necrosis factor receptor associated factor 5- (TRAF5-) induced activation of the NF-κB signaling pathway in mouse podocytes." (PMID 32184902, 2020).
experimental autoimmune encephalomyelitis (1 paper, 2018). An autoimmune demyelinating disease of the central nervous system that is produced experimentally in animals by the injection of homogenized brain or spinal cord in Freund's adjuvant. "Accordingly, Traf5−/− mice exhibited exacerbated TH17 cell-dependent neuroinflammation in a model of experimental autoimmune encephalomyelitis (EAE)." (PMID 30214449, 2018). "Traf5−/− donor CD4+ T cells exacerbate the development of neuroinflammation in experimental autoimmune encephalomyelitis (EAE) in wild-type recipient mice." (PMID 30214449, 2018).
ischemia (1 paper, 2025). A hypoperfusion of the BLOOD through an organ or tissue caused by a PATHOLOGIC CONSTRICTION or obstruction of its BLOOD VESSELS, or an absence of BLOOD CIRCULATION. "Studies have demonstrated that TRAF5 provides protection against cardiac ischemia reperfusion injury through AKT T signaling, highlighting the significant function of TRAF5 in inflammation and apoptosis." (PMID 40136419, 2025).
lentivirus infection (1 paper, 2018). Virus diseases caused by the Lentivirus genus. "Thus, the knockdown cell line (TRAF5-sh2) targeting TRAF5 was constructed using the TRAF5-sh2 vector via lentivirus infection in PAMs according to the methods described previously." (PMID 29874812, 2018).
pancreatic cancer (1 paper, 2024). "Data from online databases indicated that TRAF5 was the only gene expressed at lower levels in pancreatic cancer tissues." (PMID 38825674, 2024). "The findings from this assessment indicated that TRAF2, TRAF3, TRAF5, and TRAF7 are effective in predicting the outcomes of pancreatic cancer." (PMID 38825674, 2024). "In addition, TRAF4, TRAF5, TRAF6, and TRAF7 demonstrate correlations with the degree of pancreatic cancer differentiation." (PMID 38825674, 2024).
prostate carcinoma (1 paper, 2021). A carcinoma that arises from epithelial cells of the prostate gland. "Furthermore, TRAF5 with other elements is able to suppress the invasion and migration abilities of prostate cancer cells." (PMID 33752668, 2021).
retinal vasculitis (1 paper, 2013). Inflammation of the retinal vasculature with various causes including infectious disease; lupus erythematosus, systemic; multiple sclerosis; behcet syndrome; and chorioretinitis. "Further stratified analysis according to the clinical and laboratory observations suggested that rs12569232/TRAF5 may play a role in the development of retinal vasculitis." (PMID 24020968, 2013).
toxoplasmosis (1 paper, 2022). A parasitic disease contracted by the ingestion or fetal transmission of toxoplasma gondii. "In addition, the TNF-signaling (bta04668; TRAF5/CREB5/CASP7/CHUK) and the toxoplasmosis (bta05145; TGFβ2/CHUK/CIITA/SOCS1) pathways were significantly enriched." (PMID 35464478, 2022).
tumor (19 papers, 2019 to 2025). "Accumulating studies have demonstrated that TRAF5 is implicated in tumor cell proliferation, apoptosis, and metastasis." (PMID 37366426, 2023). "P.g. also manipulates inflammatory signaling in SCC-25 cells by activating NF-κB and MAPK pathways, driving tumor-associated inflammation and metastasis via upregulation of CCL20, TNFAIP6, CXCL8, TNFAIP3, TRAF5, CYP1A1, and NOD2 gene expression." (PMID 40924302, 2025). "In contrast, the proteins CAMK2A, IL33, IRF9, and TRAF5 were primarily expressed in normal tissues and exhibited reduced expression in tumor tissues." (PMID 40893939, 2025). "M2-tumor-associated macrophages promote METTL3 expression and increase the m6A RNA content of TNF receptor-associated factor 5 (TRAF5), affecting the tumor microenvironment, promoting necroptosis, and leading to acquired oxaliplatin tolerance." (PMID 38988324, 2024). "In the context of HNSC, our findings indicate that TRAF1 and TRAF5 act as tumor suppressors, whereas TRAF2 emerges as an oncogenic factor." (PMID 38825674, 2024). "G6PD is mainly expressed in TAMs, LAPTM4B is predominantly expressed in tumor endothelial cells (TECs), GBA is expressed in both cell populations, and TRAF5 is primarily expressed in cancer-associated fibroblasts (CAFs)." (PMID 38170006, 2023). "Immunohistochemistry demonstrated the decreased expression of Ki67 (a cell proliferation marker) in xenograft tumor tissues by sh-TRAF5." (PMID 37366426, 2023). "Collectively, these findings imply that down-regulation of TRAF5 can restrain tumor growth, suppress cell proliferation, and promote cell necroptosis in HCC." (PMID 37366426, 2023). "Our data showed that down-regulation of TRAF5 inhibited xenograft tumor growth, as the volume and weight of xenograft tumors were decreased following TRAF5 deficiency." (PMID 37366426, 2023). "The qRT–PCR experiments indicated that TRAF4 and TRAF5 mRNA levels were relatively higher in the tumour tissues." (PMID 34983361, 2022). "Silencing TRAF5 or elevating miR-34a-3p expression mitigated up-regulated DDX11-AS1-mediated promotion of tumor growth." (PMID 33752668, 2021). "The expression of EPHB2, IL-13, MAP2, RPN2, and TRAF5 was correlated with microsatellite instability (MSI), while the expression of IL-13, RPN2, and TRAF5 was related to tumor mutation burden (TMB)." (PMID 33937013, 2021). "In summary, the study concludes that silenced DDX11-AS1 or up-regulated miR-34a-3p inhibits the growth of HCC cells and represses the tumor growth in nude mice via repression of TRAF5." (PMID 33752668, 2021). "The outcomes implied that down‐regulation of HDAC3 elevated miR‐495‐3p to suppress tumour growth in vivo through declining TRAF5." (PMID 33048450, 2020). "Moreover, TRAF5 knockdown suppressed xenograft tumor growth, inhibited cell proliferation, and promoted tumor cell apoptosis." (PMID 37366426, 2023). "Additionally, Ki67 protein expression (a signature of cell proliferation) in xenograft tumor tissues was reduced after TRAF5 knockdown." (PMID 37366426, 2023). "Similarly, at PCa study, miR-141-3p has been found down regulated, acting as a tumor suppressor that targets TRAF5 and TRAF6." (PMID 33413466, 2021). "Specifically, CHMP4C, IRF9, and TRAF5 may function as tumor suppressors." (PMID 40893939, 2025). "Besides, sh-TRAF5 promoted cell apoptosis in xenograft tumor tissues." (PMID 37366426, 2023). "The volume and weight of xenografted tumor in nude mice injected with HCC cells were decreased after co-transfection of pcDDX11-AS1 and miR-34a-3p mimic, or that of pcDDX11-AS1 and sh-TRAF5." (PMID 33752668, 2021). "The functions of these genes, namely CD40, MAP2K6, TRAF5, PI3K2R, have been reported in enhancing cell proliferation and tumor growth/metastasis." (PMID 31349612, 2019). "Also, it was measured that miR-34a-3p mimic or sh-TRAF5 reversed the influence of pcDDX11-AS1, thus to reduce Ki67 and increase Caspase-3 expression in tumor tissues." (PMID 33752668, 2021).
tumor (continued). "Importantly, we discovered TRIM8, DTX2, and TRAF5 as the most vital contributors from the RNF family, which were related to immune infiltration in LGG tumor immune landscape." (PMID 35223862, 2021).